TRBJ2-3 (T cell receptor beta joining 2-3)
Description:
J region of the variable domain of T cell receptor (TR) beta chain that participates in the antigen recognition. Alpha-beta T cell receptors are antigen specific receptors which are essential to the immune response and are present on the cell surface of T lymphocytes. Recognize peptide-major histocompatibility (MH) (pMH) complexes that are displayed by antigen presenting cells (APC), a prerequisite for efficient T cell adaptive immunity against pathogens. Binding of alpha-beta TR to pMH complex initiates TR-CD3 clustering on the cell surface and intracellular activation of LCK that phosphorylates the ITAM motifs of CD3G, CD3D, CD3E and CD247 enabling the recruitment of ZAP70. In turn ZAP70 phosphorylates LAT, which recruits numerous signaling molecules to form the LAT signalosome. The LAT signalosome propagates signal branching to three major signaling pathways, the calcium, the mitogen-activated protein kinase (MAPK) kinase and the nuclear factor NF-kappa-B (NF-kB) pathways, leading to the mobilization of transcription factors that are critical for gene expression and essential for T cell growth and differentiation. The T cell repertoire is generated in the thymus, by V-(D)-J rearrangement. This repertoire is then shaped by intrathymic selection events to generate a peripheral T cell pool of self-MH restricted, non-autoaggressive T cells. Post-thymic interaction of alpha-beta TR with the pMH complexes shapes TR structural and functional avidity.
Synonyms: TRBJ23; TCRBJ2S3
Gene: T-cell receptor joining (J) gene on chromosome 7 (142,796,847 to 142,796,895, forward strand). Ensembl gene ENSG00000211767.
Subcellular location: Cell membrane
Gene Ontology:
Cellular component: plasma membrane
Diseases named in the same sentence as TRBJ2-3 in open-access papers:
TRBJ2-3 is named in the same sentence as 2 diseases in open-access papers, as found by Europe PMC text mining. Sharing a sentence is not in itself a finding about the gene and the disease. The quoted sentences say what the papers report.
bacterial infection (1 paper, 2023). "PRP also upregulated the genes involved in the beta chain of the T cell receptor (TRBV3‐1, TRBV6‐5, TRBV7‐2, TRBV27, TRBC2, and TRBJ2‐3), which is responsible for antigen recognition and activation of cellular immunity during bacterial infection." (PMID 36704119, 2023).
tumour (1 paper, 2018). "Here we show that the structures of two distinct TCRs (TRAV4+TRAJ21+-TRBV28+TRBJ2-3+ and TRAV4+TRAJ8+-TRBV9+TRBJ2-1+), originating from a polyclonal T-cell repertoire, bind to HLA-B*07:02, presenting a 13-amino-acid-long tumour-associated peptide, NY-ESO-160–72." (PMID 29531227, 2018).